CRP (C-reactive protein)
Diseases named in the same sentence as CRP in open-access papers (continued):
Sharing a sentence is not in itself a finding about the gene and the disease.
asthma (continued). "Patients were followed up after 3 months and assessed regarding clinical outcomes, asthma control tests (ACTs), pulmonary function test parameters, C-reactive protein (CRP) levels, frequency of asthma attacks, ED visits, and hospitalization rate." (PMID 40787554, 2025). "In the asthma group, the decrease in the proportion of patients with CRP levels above the reference level was observed at the trend level (p = 0.06)." (PMID 39937802, 2025). "Similar results were observed for asthma severity, and levels of BEC, ECP, hc-CRP, and total IgE (higher levels were associated with allele C)." (PMID 39871194, 2025). "Elevated eosinophil counts and CRP levels play a critical role in the frequency and severity of asthma exacerbations and overall asthma prognosis." (PMID 40770020, 2025). "FeNO is used as a tool for tailor-made asthma management, and CRP is a marker of systemic inflammation." (PMID 40662069, 2025). "Fewer studies correlated elevated CRP with increased vascular inflammation, cardiovascular events, and worse asthma control, suggesting that CRP-based assessment of the global disease burden in patients with comorbid asthma and OSA is feasible." (PMID 40662069, 2025). "CPAP therapy reduced CRP by 1.8 mg/L (p = 0.003) in OSA-asthma patients, underscoring its anti-inflammatory role." (PMID 40662069, 2025). "For instance, several studies reported reduced positive effects of continuous positive airway pressure (CPAP) therapy for OSA and decreased concentration of CRP, which can control asthma in patients with OSA." (PMID 40662069, 2025). "These patients can be regarded as having potentially more severe inflammatory processes, both in the airways and in the general circulation, and thus require more intensive treatment of asthma to achieve CRP reduction." (PMID 40662069, 2025). "FeNO is a sign of eosinophilic airway inflammation that is characteristic of asthma, while CRP is an inflammatory general biomarker that is increased in both asthma and SDB." (PMID 40662069, 2025). "In the present study, we aimed to investigate the effects of metformin on clinical outcomes, asthma control tests (ACTs), pulmonary function tests (PFTs), BS control, and C-reactive protein (CRP) levels in patients with concurrent asthma and MetS." (PMID 40787554, 2025). "Studies have reported that CRP is elevated in asthmatics, and is related to poor asthma control, frequent exacerbations and systemic inflammation." (PMID 40662069, 2025). "In what follows we will focus on physio pathological correlations of FeNO and CRP with asthma and sleep apnea." (PMID 40662069, 2025). "Purpose of this study is to investigate dynamics of CRP, serum cytokines (IL-2, IL-6, IL-10, IL-17) in patients with asthma and COPD, as well as to perform a correlation analysis with the clinical manifestations of the diseases within a year after vaccination." (PMID 39937802, 2025). "It has been established that CRP levels are high in asthmatic patients and such patients have more uncontrolled asthma, frequent exacerbations and other complications." (PMID 40662069, 2025). "It has been noted that patients with asthma who have undergone physical activity have reduced serum C‐reactive protein (CRP), exhaled nitric oxide (FeNO), and sputum eosinophil counts (EOS)." (PMID 40242882, 2025). "Highly sensitive CRP was found to be higher in 45 patients with asthma compared to healthy subjects, and significantly correlated with eosinophils and neutrophils in the sputum." (PMID 38256660, 2024). "Aside from asthma tests, other tests that were considered less useful included vitamin D, allergy, and C reactive protein (CRP) tests." (PMID 38499294, 2024). "Age, CRP, platelet, total bilirubin, and the prevalence of underlying COPD, asthma, liver cirrhosis, DM, and solid organ malignancy among the four IPA groups were similar." (PMID 38436032, 2024).
asthma (continued). "The authors concluded that an abnormal chest X-ray or an elevated CRP level indicates a potentially serious outcome, especially in patients registered as obese or who have lung diseases other than asthma or COPD." (PMID 38408061, 2024). "On the other hand, clinical studies have found that the levels of inflammatory factors such as C‐reactive protein (CRP) in the peripheral blood of children with asthma are significantly higher than those of non‐asthmatic patients." (PMID 38687096, 2024). "In contrast, the asthma population had higher levels of inflammatory factors, including C-reactive protein (CRP) and tumor necrosis factor alpha (TNF-α)." (PMID 39459579, 2024). "A total of five predictor variables were screened, including CRP > 10 mg/L, fibrinogen > 4 g/L, white blood cell >10 × 109/L, fever, use systemic corticosteroids before admission, and early‐onset asthma." (PMID 37793902, 2023). "The study suggests that trans fatty acids have been shown to increase airway inflammation and circulating CRP levels in asthma patients." (PMID 37720383, 2023). "The six independent predictors included elevated levels of white blood cells, fibrinogen, and CRP, as well as fever, use of systemic corticosteroids before admission, and early‐onset asthma." (PMID 37793902, 2023). "Increases in CRP as large as 300% have been reported during a naturally occurring asthma exacerbation (compared to remission)." (PMID 37459335, 2023). "Hs-CRP was significantly higher in the uncontrolled asthma group at 0.005 ± 0.004 mg/ml compared to 0.002 ± 0.003 mg/ml and 0.002 ± 0.005 mg/ml partly-controlled, and well-controlled groups (p-value=0.002) among groups." (PMID 37519504, 2023). "Early‐onset asthma, fever, use systemic corticosteroids before admission, and some markers (the increased white blood cell, fibrinogen, and C‐reactive protein [CRP]) were independent predictors of CAP in patients hospitalized for AEs." (PMID 37793902, 2023). "Zhu’s research also showed that the NLR index increases with the CRP parameter, especially in asthma exacerbations." (PMID 37959334, 2023). "Early‐onset asthma, fever, use of systemic corticosteroids before admission, and some markers (increased levels of white blood cells, fibrinogen, and CRP) were independent predictors of CAP in patients hospitalized for AEs." (PMID 37793902, 2023). "Recently, similar results were obtained in severe asthma patients, where miR-125b highly correlated with high-sensitivity CRP (hsCRP)." (PMID 35872885, 2022). "In the genetic correlation analysis, we found that adiponectin was only significantly associated with childhood-onset asthma, whereas CRP, IGF-1, leptin, and TNFR2 were only significantly associated with adult onset asthma." (PMID 36253437, 2022). "A recent study found a highly significant correlation between the increased expression of miR-125b and CRP/IgE levels (r = 0.86/r = 0.68; p < 0.0001) in asthma patients, indicating the potential relevance of this miRNA for particular asthma phenotypes." (PMID 35455659, 2022). "FEV1, total lung capacity, functional residual capacity, asthma control, and systemic inflammation markers (CRP and leptin) were improved in the asthma group with BS." (PMID 36551211, 2022). "Compared to severe asthma noAand/orD, hs-CRP levels were significantly higher in severe asthma + D (10.8." (PMID 36510255, 2022). "A highly significant correlation between the expression of miR-125b and CRP/IgE levels (r = 0.86/r = 0.68; p < 0.0001) in asthma patients indicates the usefulness of this molecular marker for asthma diagnosis." (PMID 34001212, 2021). "In our case, the history of autoimmune pancreatitis and asthma, normal level of IgA (51 mg/dL at the first diagnosis of IgG4-RD) and CRP, high level of IgE (267.5 mg/dL at first diagnosis of IgG4-RD) and asymptomatic condition suggest IgG4-RD rather than MCD." (PMID 32705358, 2020).
asthma (continued). "In our study, positive correlation between BPI and hs-CRP was found in the asthma patients after LD-adjusted Bonferroni correction." (PMID 32565845, 2020). "After LD-adjusted Bonferroni correction, the correlation between BPI and hs-CRP was still confirmed in the asthma patients." (PMID 32565845, 2020). "We considered high CRP levels as an indicator of ongoing infection and inflammation and found that children with asthma and a CRP value over 5 mg/L had a significantly higher PD‐L1 mRNA expression in total blood cells as compared to the control children." (PMID 32394602, 2020). "While increased systemic inflammation has been reported in some studies of asthma, this was only significant in CRP between our two groups." (PMID 31892115, 2019). "The intervention group had significantly decreased body fat percent, visceral fat, weight, and BMI compared with the control group and displayed reduced leptin and CRP and improved asthma control and lung function." (PMID 30400197, 2018). "Lung function, anthropometrics, maximal oxygen uptake (VO2max), asthma severity, fat percentage, and systemic markers (leptin, adiponectin, and CRP) were measured at baseline, 6 months, and 12 months." (PMID 30400197, 2018). "The percentage of subjects having increased CRP was significantly higher in the COPD group than that in either the asthma or ACO groups (54% versus 13.1% and 23.7%; P < 0.001 and P < 0.01, resp.)." (PMID 29808101, 2018). "It is also unlikely that false positives would occur differentially for different tertiles of IL-6 or CRP, or by asthma/eczema diagnosis." (PMID 27476619, 2017). "In our study, the hypercoagulable state in asthma was potently and independently determined by increased blood C-reactive protein (CRP) concentrations." (PMID 28429138, 2017). "A recent study on gene expression of blood CD4+ T cells from patients with depression and asthma showed that the main active pathways in depressive asthma are those related to acute phase protein signalling (such as IL-6 and CRP signalling)." (PMID 27212806, 2016). "Neutrophilic asthma had raised CRP and fibrinogen while eosinophilic asthma only showed raised fibrinogen compared to healthy subjects (p < 0.005)." (PMID 27044366, 2016). "Increased serum levels of CRP and SAA are also associated with airway inflammation, asthma and chronic obstructive pulmonary disease." (PMID 26792395, 2016). "Neutrophilic asthma was characterized by raised CRP and fibrinogen levels, while eosinophilic asthma had raised fibrinogen only, compared with healthy subjects." (PMID 27044366, 2016). "In well controlled asthma the hs-CRP decreased significantly compared with poorly controlled (P=0.024) but still was higher than control (P=0.017)." (PMID 26958331, 2016). "Elevated IL-6, CRP, and soluble CD163 (macrophage activation marker) have been associated with reduced lung function (especially in severe asthma) and neutrophilic airway inflammation." (PMID 27212806, 2016). "In this study the patients with COPD or asthma exacerbations were, as a routine, tested with the following three biomarkers: CRP test, spirometry and pulse oximetry." (PMID 25887285, 2015). "Several previous studies have demonstrated an association between serum CRP and lung function parameters (FEV1 (% predicted), FVC (% predicted) or FEV1/FVC (%)) in asthma." (PMID 24073339, 2013). "Elevated serum levels of reactive C-reactive protein (CRP) are considered markers of systemic inflammation either in COPD or in asthma." (PMID 24004921, 2013). "Beside airway inflammation, several studies have indicated a positive relationship between asthma and increased CRP levels." (PMID 24073339, 2013). "In agreement with previous reports, we found significantly higher plasma CRP levels at acute exacerbation and remained elevated during remission compared with healthy controls, reflecting chronic systemic inflammation in asthma." (PMID 24073339, 2013).
asthma (continued). "The potential value of CRP, suPAR and IL-6 in the determination of asthma control was analyzed using ROC analysis." (PMID 23565268, 2013). "In asthma, the level of CRP is proved to be useful in tracking the scope of systemic inflammation." (PMID 40662069, 2025). "Furthermore, adolescent studies on asthma biomarkers have typically focused on more traditional inflammatory markers such as C-reactive protein (CRP) or eosinophil counts, with limited consideration of lipid-based ratios or indices." (PMID 40546825, 2025). "The association between the administration of systemic antibiotics during the neonatal period and the diagnosis of FA was analyzed, adjusting for inflammatory parameters at presentation (CRP levels at admission), maternal atopy history (maternal asthma or food allergy), and SES." (PMID 40259094, 2025). "However, in the multivariable model, only Black race and CRP were positively correlated with the probability of high IL-6 asthma." (PMID 39714726, 2025). "High-sensitivity CRP is the marker of inflammation in both asthma and cardiovascular disease (CVD)." (PMID 40217808, 2025). "Patients with asthma and high IL-6 were more likely to be Black and showed increased CRP." (PMID 39714726, 2025). "It is observed that the mean values for the biological variables of the investigated patients are within the reference biological range, with slight modifications regarding the CRP concentrations for the group of patients with partially controlled asthma (CRP = 9 mg/L)." (PMID 40507769, 2025). "Recent studies highlight distinct CRP patterns in comorbid asthma-SAS." (PMID 40662069, 2025). "Multivariable analysis of FEV1 (Supplement) and FVC (Supplement) revealed negative associations with Black race, female sex, CRP, IL-6, HbA1c, metabolic dysfunction, age, and current asthma, and a positive association with height." (PMID 39714726, 2025). "CRP level is higher in those patients with both conditions as compared to patients with asthma alone that may imply that the systemic inflammation associated with sleep apnea can exacerbate the inflammatory state of asthma." (PMID 40662069, 2025). "In addition, FeNO and CRP are useful to classify the severity and inflammatory component of asthma and sleep apnea in clinic." (PMID 40662069, 2025). "Furthermore, CRP levels progressively rise in correlation with the severity of the condition in children undergoing acute asthma attacks." (PMID 41458088, 2025). "In patients with asthma, CRP is a marker of the extent of systemic inflammation, if present." (PMID 40662069, 2025). "Hence besides measuring asthma control, CRP has been known for quite sometimes to be a cardiovascular disease risk indicator." (PMID 40662069, 2025). "This means that general CRP readings could be much higher in patients with both asthma and sleep apnea than in those with only one or the other disease." (PMID 40662069, 2025). "Moreover, many studies have described the role of FeNO and CRP in asthma and sleep apnea; however, few studies have investigated the interconnection between these biomarkers in asthma and sleep apnea syndrome." (PMID 40662069, 2025). "Moreover, in the severe group with asthma, CRP levels were lower (113.26 ± 76.33 mg/L) in comparison to the group without asthma (154.08 ± 104.90 mg/L)." (PMID 38750426, 2024). "Indeed, markers of acute inflammation, such as C-reactive protein (CRP), are elevated in exhaled breath condensate during naturally occurring asthma exacerbations, and are correlated with CRP levels measured systematically at the same time-points." (PMID 37459335, 2023). "Furthermore, the importance of circulating HS-CRP (high sensitivity C-reactive protein) in the diagnosis of asthma is increased when paired with fractional exhaled nitric oxide (FeNO)." (PMID 37627950, 2023).
asthma (continued). "However, differentiation with sarcoidosis is readily achieved based on the history of asthma (often severe), marked blood eosinophilia, serum C-reactive protein elevation, and positive assays for perinuclear antineutrophil cytoplasmic antibodies." (PMID 37250639, 2023). "The PRS of the three-SNP model was associated with WBC counts and asthma but not serum CRP concentration and MetS-related biochemical parameters." (PMID 37686882, 2023). "A cross-section study based on NHANES data conducted in adults indicates that high-fiber diet may reduce the serum CRP level and decrease odds of having asthma." (PMID 37720377, 2023). "One such marker is C-reactive protein (CRP), a potential biomarker of asthma control." (PMID 38274547, 2023). "Furthermore, our data reveals enhanced expression of IL6R and CRP in AECs derived from atopic-asthma patients." (PMID 37860000, 2023). "However, PRM analysis results showed that the CRP level in the EGPA group was significantly higher than that in the severe-asthma group." (PMID 35757752, 2022). "After adjusting for age, sex, ethnicity, TV/computer usage, serum vitamin D level, serum vitamin A level, and education attainment, we found that neither C-reactive protein nor asthma was associated with myopia or high myopia." (PMID 36229775, 2022). "In this present study, we found that neither C-reactive protein nor asthma increased the risk and severity of myopia, which partially contradicted previous studies." (PMID 36229775, 2022). "Likewise, patients with severe asthma had increased baPWV and CRP compared to patients with stable asthma and control subjects." (PMID 33608061, 2021). "Another two studies found an association between SSB intake and higher levels of CRP in females, but not in males in a cohort of healthy participants, and IL-17F in both males and females from a cohort of patients with asthma." (PMID 33503979, 2021). "Additionally, asthma patients complained less frequently about sputum, had higher eosinophil count and lower serum CRP value at presentation." (PMID 34575644, 2021). "Results showed adequate adherence was associated with lower levels of CRP, IL-6, and TNF-α, and soluble vascular cell adhesion molecule-1 (sVCAM-1) in healthy males and females, and IL-17 in both males and females with asthma." (PMID 34825233, 2021). "In conclusion, the data presented here may suggest that expression of miR-125b in the exosomal fraction of plasma and its correlation with serum CRP and total IgE is promising as a molecular marker for the diagnosis of severe asthma." (PMID 34001212, 2021). "BPI levels were increased in asthma and positively correlated with hs-CRP." (PMID 32565845, 2020). "For this prediction model, 6 factors (FEV1/FVC ratio, frequency of waking due to asthma symptoms, hs-CRP, eosinophil, basophil, weight, smoking condition) out of 18 input parameters were identified and used to classify the patients in five groups from low to high level of effect." (PMID 32628613, 2020). "After that, we turn to a more detailed discussion of the significant results (pulmonary pathologies: asthma and lung diseases; immunological impairments: raised CRP values; physical functional limitations and ADL and IADL disability) and situate these within the Indonesian context." (PMID 32736632, 2020). "Studies linking maternal CRP with childhood asthma/allergies have also been inconsistent." (PMID 32354366, 2020). "However, differences between CRP levels in AD patients and controls remained highly significant after exclusion of all the patients with a history of asthma." (PMID 29188018, 2017). "On the other side, when hs-CRP is ≤61 mg/L, other diagnostic hypotheses, including COPD exacerbation, asthma and acute heart failure, might be pursued." (PMID 26772604, 2016). "A population based study demonstrated a significant inverse association between FEV1 and forced vital capacity with CRP in both men and women independent of smoking, asthma and body mass index." (PMID 26958331, 2016).